ENSG00000289766 (novel protein)
Gene: Protein-coding gene on chromosome 12 (13,088,784 to 13,103,484, reverse strand). Ensembl gene ENSG00000289766.
Homologues: Orthologues: mouse Gm56924 (74% identical).